NECTIN4 (nectin cell adhesion molecule 4)
Diseases named in the same sentence as NECTIN4 in open-access papers (continued):
Sharing a sentence is not in itself a finding about the gene and the disease.
breast carcinoma (continued). "We observed the expression of nectin-4 on the surface of tree shrew mammary tumor cells." (PMID 32421739, 2020). "We have also confirmed the expression of nectin-4 in some mammary tumor cells." (PMID 32421739, 2020). "Furthermore, the levels of both two forms of Nectin-4 can be used as important biomarkers and prognostic predictors for breast cancer patients." (PMID 31043861, 2019). "Interestingly, moderate (26%) and strong (27%) Nectin-4 expression was seen most frequently in bladder cancer, followed by breast cancer (53%, n = 654)." (PMID 31572728, 2019). "Nectin 4 was overexpressed in triple negative breast cancer and basal breast cancer patients." (PMID 31137558, 2019). "This strengthens our hypothesis that the expression of Nectin-4 isoform would sensitize a subset of breast cancer cells to lapatinib." (PMID 29066719, 2017). "In addition, the knockdown of Nectin-4 by transfection of siRNA or the intravenous injections of anti-Nectin-4 monoclonal antibody inhibits tumor growth and reduces cell-cell contact in breast cancer cell lines in vivo." (PMID 25888293, 2015). "We then studied Nectin-4 expression in normal breast epithelium and breast carcinoma." (PMID 17474988, 2007). "By contrast, Nectin-4 was expressed in 61% of ductal breast carcinoma vs 6% in lobular type." (PMID 17474988, 2007). "However, we found i) that our mAbs display a good sensitivity in ELISA experiments, ii) a good correlation between Nectin-4 mRNA and protein level in breast cancer cell lines, and iii) that the TACE protease is weakly expressed in the normal mammary gland." (PMID 17474988, 2007). "Nectin-4 is a new bio-marker whose use could help refine breast cancer taxonomy and improve patients' follow-up." (PMID 17474988, 2007). "Nectin-4 emerges as a potential target for breast cancer immunotherapy." (PMID 17474988, 2007). "Nectin-4 may be a new histological and serological marker in breast carcinoma, but its function is unclear." (PMID 17474988, 2007). "Therefore, exploring the interaction between Nectin-4 and survivin in breast cancer may provide value for the treatment of breast cancer in the future." (PMID 38606099, 2024). "Nectin-4 has shown clinical significance in serological and molecular imaging diagnosis of some tumor types, such as ovarian cancer, urothelial carcinoma, and breast cancer, but more studies with larger sample sizes are needed to promote its further applications." (PMID 38606099, 2024). "Supporting the role of nectin-4 in cancer progression, it has been shown that blocking nectin-4 with antibodies could inhibit the growth of cell line-derived and patient-derived breast cancer mouse xenografts and augment the antitumor activity of NK cells." (PMID 38288120, 2023). "In addition, both scFvs could diminish attachment-free cell aggregation of nectin-4-positive breast cancer cells." (PMID 38288120, 2023). "To evaluate the application of L4 and S21, we next examined whether these scFvs could detect endogenous nectin-4 expressed in human breast cancer cell lines, including MCF-7 (luminal type A), BT-474 (luminal type B HER2-positive), and MDA-MB-453 (triple negative)." (PMID 38288120, 2023). "It is noteworthy that nectin-4 expression is increased in some cancer types, such as lung, bladder, and breast cancer (BC) and its higher expression is related to a poorer prognosis for cancer patients." (PMID 36497240, 2022). "Nectin-4 could promote migratory processes in breast cancer physiopathology." (PMID 17474988, 2007). "We tested whether detection of soluble Nectin-4 may be used to monitor breast cancer progression." (PMID 17474988, 2007). "In conclusion, several reports by our group and others demonstrate that lactate plays an important role in breast cancer motility in part through modulating EMT status, and the expression profile of cytokines, adhesion molecules, MMP-2, and nectin-4." (PMID 40507273, 2025).
breast carcinoma (continued). "Beyond HER2 and TROP2, alternative targets being evaluated for novel breast cancer ADCs in phase I‐II trials include HER3, B7‐H3, B7‐H4, CD166, folate receptor‐α, LIV‐1, nectin‐4, ROR1 (NCT04504916), and ROR2 (NCT03504488)." (PMID 41361931, 2025). "Repeated treatment with the ADC N41mab-vcMMAE, which targets nectin-4 and has MMAE as its payload, in mice xenografted with the SUM190 breast cancer cell line induced refractory tumors which were found to overexpress ABCB1 as the mechanism of resistance." (PMID 40501953, 2025). "The highest prevalence of NECTIN4 amplifications was found in bladder cancer (BLCA, 17%), cholangiocarcinoma (CHOL, 14%), hepatocellular carcinoma (LIHC, 12%), breast cancer (BRCA, 9%), and lung adenocarcinoma (LUAD, 7%)." (PMID 38657187, 2024). "Breast carcinomas express abundantly cell surface CD46 and nectin-4, both utilized as cell entry receptors by the vaccine strain of measles, particularly viruses of the Edmonston vaccine lineage." (PMID 39339989, 2024). "The soluble nectin-4 ectodomain, which could be detected in the sera of breast cancer, lung cancer, and ovarian cancer patients, has been shown to interact with endothelial integrin β4 to promote angiogenesis in breast cancer through the Src-regulated PI3K/Akt pathway." (PMID 38288120, 2023). "Nonetheless, considering nectin-4’s contribution to cell-to-cell attachment and tumor cells’ anchorage-independent growth, we then performed a clustering assay to evaluate whether the scFvs could inhibit breast cancer cell aggregation, which is important for tumor formation." (PMID 38288120, 2023). "We previously showed using human breast cancer T47D and SUM190-PT cells that nectin-4 cis-interacts with ErbB2 and enhances its homo-dimerization and activation in a novel mechanism, activating the PI3K-AKT signaling and enhancing DNA synthesis." (PMID 33795719, 2021). "Similar dynamic change was observed in nectin cell adhesion molecule 4 (NECTIN4) and secreted phosphoprotein 1 (SPP1), which have been identified previously as markers for breast cancer progression or metastasis." (PMID 33004987, 2020). "Nectin-4 represents a potential target in TNBC, and its role in molecularly defined breast cancer subtypes should be investigated in larger patient cohorts." (PMID 31572728, 2019). "Multiple novel PDC agents are currently in clinical development, including TH1902 (targeting SORT1-positive advanced solid tumors, phase I trial), ANG1005 (for breast cancer brain metastases, phase II trial), and BT8009 (targeting nectin-4, phase I/II clinical trials)." (PMID 41001098, 2025). "In breast cancers, homotypic CTC clusters demonstrate remarkable resilience against anoikis by preserving cell–cell contacts through a variety of complexes, including plakoglobin (JUP), homophilic CD44 interactions, E-cadherin (CDH1) and nectin-4." (PMID 38506114, 2024). "A study on 197 patients with primary unilateral breast cancer (without involved lymph nodes or distant metastasis) found that 34 patients had Nectin-4 expression on the tumor cell membrane." (PMID 38606099, 2024). "Our initial results indicated that the scFvs are not significantly cytotoxic to nectin-4-positive and nectin-4-negative breast cancer cell monolayers." (PMID 38288120, 2023). "Numerous studies confirmed that Nectin-4 could facilitate tumor growth, angiogenesis, and metastasis through phosphoinositide 3-kinase/protein kinase B (PI3K/AKT) signaling cascade in breast cancer, gallbladder carcinoma, and colorectal cancer." (PMID 35953862, 2022). "Nectin-4 expression levels of breast cancer cells (MDA-MB-468: TNBC cells; and MCF-7, non-TNBC cells) were proved by western blot, flow cytometry, and immunofluorescence imagning." (PMID 35614462, 2022).
breast carcinoma (continued). "It is known that cancer cell-specific molecules known as cancer antigens such as EGFR (colorectal cancer), GD2 (neuroblastoma), HER2 (breast cancer), VEGFR2 (gastric cancer), Nectin-4 (bladder cancer), or TROP2 (triple-negative breast cancer) are expressed on the surface of cancer cells." (PMID 36546903, 2022). "Nectin-4 has been also described as a marker of cancer stem cells (CSC) and EMT, induced by Wnt/β-catenin signaling as well as anchorage-independent cell proliferation in human breast cancer." (PMID 34680588, 2021). "In addition, Nectin-4 represents a potential target in TNBC, and its role in molecular defined breast cancer subtype should be investigated in larger patient cohorts." (PMID 31572728, 2019). "Secondly, we did not investigate the role of high expression of Nectin-4 in other molecular breast cancer subtypes and not on a DNA or mRNA level." (PMID 31572728, 2019). "Because there is no early marker for breast carcinoma, we looked for the presence of soluble Nectin-4 in the serum of patients with non-MBC." (PMID 17474988, 2007). "Nectin-4 can be detected in patients negative for both markers or positive for only one marker and thus represents a complementary marker for breast carcinoma." (PMID 17474988, 2007). "A major interest of Nectin-4 in breast cancer physiopathology is that this protein is undetectable in normal breast epithelium by IHC." (PMID 17474988, 2007). "The nectin-4-negative MDA-MB-231 breast cancer cells served as a negative control." (PMID 38288120, 2023). "Notably, L4 produced little background in the nectin-4-negative MDA-MB-231 breast cancer cell, whereas S21 generated higher background (data not shown)." (PMID 38288120, 2023). "Importantly, while the scFvs are non-cytotoxic, they could inhibit the self-clustering of nectin-4-positive breast cancer cells." (PMID 38288120, 2023). "produced a recombinant MV (rMV-SLAMblind) that bound to Nectin-4 but not its original primary receptor SLAM; it also infected and suppressed the growth of subcutaneous xenograft models of various cancers, including breast cancers such as TNBC." (PMID 38606099, 2024).
bladder cancer (51 papers, 2018 to 2026). "In bladder cancer, ADCs have demonstrated remarkable efficacy by targeting specific tumor-associated antigens, such as nectin-4 and HER2, thereby inducing tumor cell apoptosis and inhibiting metastasis." (PMID 40433388, 2025). "Our study revealed that, in bladder cancer, progression from non‐muscle‐invasive to muscle‐invasive and metastatic is associated with decreased Nectin‐4 expression and increased ABC transporter expression." (PMID 39877564, 2025). "Nectin-4, a tumour-associated antigen, has been shown to be selectively overexpressed in urothelial cancer, present in approximately 83% of bladder cancers and up to two-thirds of upper tract urothelial cancers, and associated with a poor prognosis." (PMID 39858014, 2025). "Nectin-4 can be detected on the surface of almost all urothelial cancer (UC) cells and in most variant bladder cancer types." (PMID 36136143, 2022). "As Nectin-4 appears to be a promising target for novel therapies in conventional bladder cancer, we aimed to analyze the expression of Nectin-4 and its prognostic value in variant histologies of bladder cancer." (PMID 36139571, 2022). "In bladder cancer, a malignancy with high recurrence rates and limited treatment options, ADCs have demonstrated remarkable efficacy by targeting specific tumor-associated antigens such as NECTIN-4 and Human Epidermal Growth Factor Receptor 2 (HER2)." (PMID 40433388, 2025). "It has been revealed that the cell surface protein NECTIN4 is a cancer-associated antigen, with the majority of human bladder carcinomas expressing moderate to high NECTIN4 protein levels (60%), while normal urothelial tissues exhibit lower (weak to moderate) NECTIN4 protein amounts." (PMID 35484425, 2022). "Studies reporting the prevalence of FGFR3 alterations and/or nectin-4 expression in bladder cancer were included." (PMID 42278538, 2026). "NECTIN4 is a cell adhesion molecule that is mainly expressed in embryonic tissues, with low expression in adult normal tissues, but shows high expression in bladder cancer, making it an ideal ADC target." (PMID 40433388, 2025). "Flow cytometry was used to evaluate the relative expression of nectin-4 in 3 human breast and 3 bladder cancer cell lines using EV as the primary antibody." (PMID 40774696, 2025). "Several studies have confirmed that Nectin-4 is upregulated particularly in bladder cancer and BC cell membranes, making it a potential target for bladder cancer and BC." (PMID 39747850, 2025). "This study demonstrates that NECTIN4-targeting CAR T cells are effective against bladder cancer, including EV-resistant cells, and their potency can be further enhanced by using rosiglitazone to boost NECTIN4 expression." (PMID 40931013, 2025). "Functional, in vitro studies in bladder cancer cell lines showed that knockdown of NECTIN4 promotes resistance to EV, validating that NECTIN4 is required for response to EV." (PMID 40422537, 2025). "In parallel, preclinical studies have shown that Nectin-4-directed ADCs can be sensitized by autophagy inhibition, with agents such as chloroquine enhancing apoptotic cell death in pancreatic and bladder cancer models [577−580]." (PMID 41184856, 2025). "In a study on nectin-4 overexpression in the human bladder cancer cell lines T24 and UM-UC-3, co-culturing these cells with nectin-4 non-expressing cell lines demonstrated the bystander effect of EV." (PMID 39891702, 2025). "Enfortumab vedotin (EV) is a groundbreaking ADC therapy targeting metastatic bladder cancer, specifically designed to bind to Nectin‐4, a cell adhesion molecule highly expressed in urothelial carcinoma." (PMID 39877564, 2025). "For instance, NECTIN-4 gene expression demonstrates heterogeneity across molecular subtypes of bladder cancer and is notably enriched in luminal subtypes." (PMID 39941802, 2025).
bladder cancer (continued). "The remarkable progress in this field is exemplified by the development of Enfortumab Vedotin (EV), an ADC targeting Nectin-4, which has redefined the therapeutic landscape for advanced bladder cancer." (PMID 40433388, 2025). "NECTIN4 amplifications are frequent genomic events in muscle-invasive bladder cancer (TCGA bladder cancer data set: approximately 17%) and mUC (approximately 26% in our mUC cohorts)." (PMID 38657187, 2024). "Two nectin-4 positive bladder cancer cells, HT1376 and SW780, were used to assess the cytotoxic effects of Nectin-4 ADC." (PMID 38664366, 2024). "In vitro and in vivo settings, our findings indicate that Nectin-4-MMAE exhibits substantial cytotoxicity on human bladder cancer cells." (PMID 38664366, 2024). "Our mRNA-seq analysis unveiled a significant upregulation of autophagy-related genes in the bladder cancer cells treated with Nectin-4-MMAE, spanning from the regulatory to the executive stages of autophagy." (PMID 38664366, 2024). "Transcriptomics showed significant alterations in autophagy-associated genes in bladder cancer cells treated with Nectin-4-MMAE, which suggested autophagy was activated by Nectin-4-MMAE." (PMID 38664366, 2024). "Nectin-4-MMAE rapidly internalized into bladder cancer cells in 30 minutes and released MMAE, inducing the onset of caspase-mediated apoptosis and leading to the inhibition of tumor cell growth." (PMID 38664366, 2024). "In a similar way, for agents like Enfortumab vedotin, targeting NECTIN-4, which is approved in bladder cancer (BLCA), high expression of this TAA is also observed in the esophagus epithelium (CESC-normal)." (PMID 39684584, 2024). "In summary, Nectin-4-MMAE showed antitumor effect via caspase-dependent apoptosis in bladder cancer cells." (PMID 38664366, 2024). "During the course of this study, we identified that autophagy serves as a cytoprotective mechanism during Nectin-4-MMAE treatment and proposed a strategy to enhance the antitumor effects of Nectin-4-MMAE in bladder cancer." (PMID 38664366, 2024). "Other promising therapeutic targets for bladder cancer include nectin-4, a cell surface protein that is overexpressed in most bladder cancer patients, and enfortumab vedotin, an antibody-drug conjugate that targets nectin-4." (PMID 37425564, 2023). "Recently, enfortumab vedotin, an ADC targeting Nectin-4, has been approved for treating patients with bladder cancer with Nectin-4 overexpression." (PMID 37345201, 2023). "In a study with patients with bladder cancer after treatment with platinum and anti programmed death 1/ programmed death ligand 1 therapy Nectin-4 expression was detected in all patient samples tested." (PMID 36268557, 2022). "As data on NECTIN4 expression in normal urothelium are scarce, further studies should investigate NECTIN4 levels in normal urothelium of bladder cancer patients as possibly relevant regarding potential side effects of enfortumab vedotin treatment." (PMID 35484425, 2022). "Our data showed that both Nectin-4 and Trop-2 are expressed in all of the subtypes of bladder cancer studied here." (PMID 34768978, 2021). "Enfortumab vedotin is another class of immunotherapy FDA approved for bladder cancer, an antibody-drug conjugate, consisting of antibodies targeting Nectin-4 conjugated with the cytotoxic agent monomethyl auristatin E (MMAE)." (PMID 33808614, 2021). "This study demonstrated, (i) the importance of Nectin-4 as a biological target for bladder cancer, relative to PD-L1, and (ii) EV has the potential to significantly extend the lives of patients, including those who failed ICI treatment." (PMID 33019653, 2020). "Similarly, Nectin-4-targeted ADCs, such as enfortumab vedotin or experimental analogues, have been investigated in preclinical models of pancreatic and bladder cancer." (PMID 41184856, 2025). "NECTIN4 is highly expressed in bladder cancer, making it an attractive target." (PMID 40422537, 2025).